CCNE1 (cyclin E1)
Diseases named in the same sentence as CCNE1 in open-access papers (continued):
Sharing a sentence is not in itself a finding about the gene and the disease.
tumor (continued). "The network of the most promising miRNA-target interactions showed that several tumor suppressor and oncogenic miRNAs target and regulate critical genes, including MYC, CREB1, TIMP3, CCNE1, and TGFB1, which were shown to be involved in WT pathogenesis." (PMID 39473825, 2024). "For example, in the tumor tissues of BLCA, CESC, and ESCA, CCNE1 expression levels are higher than normal tissues." (PMID 39591374, 2024). "According to previous studies, CT-based inter-tumor heterogeneity metrics were correlated with the enrichment of the WNT/ β-catenin signaling pathway, 19q12 amplification involving CCNE1, and abundance of some proteins in vivo." (PMID 38475819, 2024). "The cell cycle in tumors is modulated by c-Myc, which regulates the expression of downstream target molecules, including cyclin D1/2, cyclin E1, CDK4, cdc25A, and E2F1, and promotes tumor growth." (PMID 39085875, 2024). "If ERBB2 is gained, the tumor has a 90% chance of being from the pancreas; however, if ERBB2 is lost or normal CCNE1 copy-number status should be assessed." (PMID 39062773, 2024). "The pan-cancer analysis of CCNE1 can analyze the role and effect of CCNE 1 in tumor development and development from multiple perspectives, and can provide some help for clinical diagnosis, treatment and basic research." (PMID 39591374, 2024). "Silencing ILF2 expression in PDAC inhibited cell cycle progression and decreased the expression of cell cycle regulators like cyclin E1 (CCNE) and proliferating cell nuclear antigen (PCNA), hindering tumor cell proliferation." (PMID 39735599, 2024). "Based on the genetic profile of tumor tissue samples, patients with different CCNE1 amplification statuses had indistinguishable PFS (P = 0.94), while patients with CCNE1 amplification tended to have a worse OS (P = 0.055)." (PMID 37131253, 2023). "Our findings in respect to the variation of HR status and genes such as CCNE1 and MYC give a clear signal that a single biopsy to individualize treatment has the potential to significantly under-represent a patient’s unique tumor biology." (PMID 37220750, 2023). "The amplification of MYC, CCNE1, and ERBB2 was more frequently detected in CSF than in tumor tissue samples, with detection rates being 46.7% (7/15) vs 26.7% (4/15), 53.3% (8/15) vs 13.3% (2/15), and 26.7% (4/15) vs 13.3% (2/15), respectively." (PMID 37131253, 2023). "The pivotal role of STAT3 in tumor development stems from its capacity to regulate the transcription of genes involved in various key processes, such as the cell cycle (CCND1, CCNE1), metabolism (OCT1, HIF1A), and cell survival (BCL2, BCLXL, and HSP70)." (PMID 37474926, 2023). "Amplification of the chromosomal region 19q12 containing the CCNE1 gene is common (∼20%) in HGSC, which across all tumor sites ranks third in frequency after endometrial carcinosarcoma and urothelial carcinoma." (PMID 36572991, 2023). "The frequency of CCNE1 amplification, MYC amplification, CDKN2A deletion, and PTEN deletion was higher in CSF than in primary tumor tissues." (PMID 37131253, 2023). "In transcriptome-based public datasets generated from four different tumor types, R-PTP-κ expression was negatively correlated with the expression pattern and prognostic value of two known E2F1 target genes (CCNE1 and CDC25A)." (PMID 36551956, 2022). "We found that 3.8% of top down-regulated DEGs in GKO tumours were CBX7 targets, including Wnt10a, CCNE1, FGFR2, and DUSP4." (PMID 35867177, 2022). "Recently, amplification of CCNE1 or PRKCI has been reported to promote HGSOC, by enhancing an immunosuppressive tumor microenvironment in the case of PRKCI amplification, conferring chemoresistance in OV." (PMID 36201246, 2022). "In terms of immune microenvironment, we found that the expressions of AURKA, CCNA2, CCNE1, CDK1, CHEK1, and PLK1 were negatively correlated with tumor immune infiltrating cells." (PMID 36483630, 2022).
tumor (continued). "At present, some potentially predictive biomarkers have been found for CDK4/6 inhibitors, such as cyclin E1 (CCNE1), thymidine kinase 1 (TK1) mRNA expression, and circulating tumour DNA (ctDNA)." (PMID 36028895, 2022). "In contrast, the mice injected cells treated with miR-106b-5p had more considerable tumor burden than controls and displayed higher expression for Ki67, PCNA, Bcl-xL, and cyclin E1, along with a lower expression for BTG3 in tumor tissues relative to controls." (PMID 35342408, 2022). "Expressions of both cyclin E1 and PCNA in DKO tumours were also increased to a similar level as that of WT tumours." (PMID 35867177, 2022). "In tumor cells, upregulated CIRS-7 exerts its sponge effect by targeting miR-7 and upregulates its key target genes, including EGFR, CCNE1, and PIK3CD, to induce tumor cell proliferation." (PMID 36139427, 2022). "Multiregional analysis across 22 tumour types revealed frequent subclonal focal amplifications in chromosomes 1q (encompassing BCL9 and MCL1), 5p (TERT), 11q (CCND1), 19q (CCNE1) and 8q (MYC)." (PMID 36289203, 2022). "Further in vivo experiments showed that overexpression of CDR1as can upregulat Cyclin E1 (CCNE1) and PIK3CD, the key targets of miR-7, in Hep2 and AMC-HN-8 cells, increasing tumor proliferation index and facilitating tumor growth." (PMID 36483049, 2022). "In addition, we found that the expressions of AURKA, CCNA2, CCNE1, CDK1, CHEK1, and PLK1 were all positively correlated with TMB, which was consistent with previous research results, and there was a positive correlation between tumor dryness and tumor mutation burden." (PMID 36483630, 2022). "The expression levels of G6PD, Cyclin E1 and MMP9 protein were significantly increased in ACHN-G6PDOE-derived tumor tissues, whereas they were obviously decreased in Caki-1-G6PDSi-derived tumor tissues compared with the corresponding controls." (PMID 34975298, 2022). "The reduction of these genes in the R-PTP-κ-high group indicates that R-PTP-κ negatively regulates the expression of E2F1 target genes CCNE1 and CDC25A in various tumor tissues." (PMID 36551956, 2022). "Nanopore sequencing of tumor detected ten breakpoints, of which HBV was integrated into intergenic nearest CCNE1 in nine reads and into TERT promoter-TSS in one read." (PMID 34642322, 2021). "Of the 143 patient tumours harbouring SKP1 shallow deletions, ~78% (111/143) occur independent of CCNE1 amplification, while ~22% (32/143) co-occur with CCNE1 gene amplification." (PMID 33731859, 2021). "The results demonstrated that the expression levels of CCNE1, E2F1, ARHGAP11A, RUNX1T1 and FES displayed significant correlation with the tumor stage in patients with NSCLC." (PMID 33613291, 2021). "The findings in vivo further indicated that CDR1as acted as an oncogene, up-regulating the proliferation index Ki-67, EGFR, CCNE1, and PIK3CD levels, thus inhibiting the anti-tumor effects of tumor suppressor miR-7." (PMID 34830377, 2021). "Meanwhile, the expression of CCNA2 and CCNB1 was positively correlated with tumor-killing immune cells, such as CD8+ T cells.The copy numbers of CCNA2, CCNB1, CCND1, CCNE1, and CCNF was positively related to gene expression." (PMID 33996604, 2021). "Here, we apply multi‐region whole‐genome sequencing to an index case of a 4‐year‐old child whose aggressive tumour harboured high‐level, focal amplifications of MYC and CCNE1 connected by translocations." (PMID 33969640, 2021). "It is well known that CCNE1 works by forming a complex with CDK2, and the CCNE1-CDK2 complex is able to pushing cell cycle from G1 to S phase, thereby regulating tumor progression." (PMID 33676555, 2021). "Then we analyzed the correlation between transcription level of CCNE1, E2F1, ARHGAP11A, RUNX1T1, FES and tumor stage in TCGA NSCLC cohort by GEPIA 2 online website." (PMID 33613291, 2021). "HBV integration led to an evident upregulation of TERT, CCNE1, and FGB in the tumor (compared to the adjacent tissue)." (PMID 34642322, 2021).
tumor (continued). "We will show that targeting of Ccne1 alone affects several important hallmarks of HCC progression and significantly reduces tumour burden at an advanced stage." (PMID 34830835, 2021). "Since phospho-Ser/Thr phosphatase cdc25A (CDC25A), cyclin E1 (CCNE1), and Myb-like protein 2 (MYBL2) have been reported as tumour promoters and are known as cell cycle regulators in NSCLC, we focused on these genes." (PMID 33883577, 2021). "IHC revealed that positive rates of CCNE1, CCNE2, and KI67 were reduced in the xenografted tumor tissues upon the injection of Exo-miR-144 agomir compared with the injection of Exo-NC-agomir (p < 0.05)." (PMID 32102682, 2020). "Given that CDK2/cyclin E1 complex is dynamically active in S phase entry and that NF90 stabilizes cyclin E1 mRNA to accelerate S phase entrance, we postulated that CDK2 phosphorylated NF90 to affect cell cycle and tumor progression." (PMID 32123579, 2020). "In the primary tumor, 15 (35.7%), 11 (26.2%), 4 (9.5%) and 4 (9.5%) patients harbored amplifications in all 3 exons of MYC, CCND1, ERBB2 and CCNE1, respectively." (PMID 33298978, 2020). "The expression levels of CCNE1 were highly correlated with CIN70 activities (Spearman’s ρ = 0.53, P = 3.93e-10) and significantly elevated in WGD tumor samples (fold change = 1.21, P = 0.011)." (PMID 33257699, 2020). "For instance, in adrenal gland adenocarcinomas, chromothriptic events are predominantly detected on chromosomes 17, 19 and 22, affecting driver genes known to play an essential role in this tumour entity, such as PRKAR1A, MLL4, CCNE1 and ZNRF3, respectively." (PMID 32385320, 2020). "For instance, in CRC, METTL3 can promote tumor progression through enhancing the expression of either MYC or CCNE1." (PMID 33015074, 2020). "DEmRNAs, including ATAD2, KIF23, MCM4, CCNB1, and CCNE1, are highly expressed in LUAD than in corresponding non-tumor tissues." (PMID 33042838, 2020). "To assess the potential function of cyclin E1 in the tumour‐promoting functions of METTL3 in CRC, we transfected CCNE1 plasmids into HT29 and LoVo cells." (PMID 32039568, 2020). "Moreover, Yang demonstrated faster tumor growth in the CDR1as + miR-7 mimic group than in the miR-7 mimic group, and that CDR1as may regulate chemosensitivity in 5-FU-resistant BC cells by inhibiting miR-7 to regulate the miR-7 target gene cyclin E1(CCNE1)." (PMID 32765960, 2020). "Zhang reached a similar conclusion using non-small-cell lung cancer (NSCLC) and found that CDR1as functions as an oncogene that inhibits the anti-tumor effects of miR-7 by upregulation of the proliferation indices Ki-67, EGFR, CCNE1, and PIK3CD." (PMID 32765960, 2020). "The genes most frequently showing CNGs in HAS tumour tissues were TOP1 (50.0%), STK4 (45.5%), CDKN1B (40.9%), H3F3A (36.4%), MYC (22.7%), CCNE1 (22.7%), NFKBIA (22.7%), VEGFA (18.2%), CCND3 (13.6%), and E2F1 (13.6%)." (PMID 30989433, 2019). "Further investigation revealed that the downregulation of VGLL4 upregulated the expression of apoptosis-related Bcl-2 and the cell-cycle regulators Cyclin D1, Cyclin E1, and CDK8, and the upregulation of these molecules was conducive to tumor proliferation." (PMID 31748508, 2019). "It is worth noting that we observe significant anti-tumor activity with elacestrant, even in models such as WHIM43, with increased cyclin E1 expression." (PMID 31852484, 2019). "The first set of four events involves three genes, FGF2, CCNE1, RNF43, whose tumor-specific APA regulations indicate clear length modulations of the 3’ UTR in cancer." (PMID 30005633, 2018). "Multiple studies have demonstrated the tumor-promoting interplays between RSF-1 and known oncogenes or tumor suppressors, such as cyclin D1, cyclin E1, retinoblastoma (RB) and breast cancer susceptibility gene 1 (BRCA1)." (PMID 29480799, 2018). "CCNE1 amplification is observed in about 20% of HGS-OvCa and allows the identification of a tumor subgroup characterized by poor prognosis and limited response to standard treatments." (PMID 29389895, 2018).
tumor (continued). "Some of these amplified genes are well-known tumor related genes, such as AKT2, FGFR3, FGF10, SDHA, CCNE1, PI3KCA, and etc." (PMID 28029662, 2017). "In cancer cells, cyclin E1 levels are up-regulated and, conversely, p16 levels was limited via various ways so that CBX7 acts as a tumor repressor in part of GBM cells." (PMID 28460453, 2017). "Many HBV integration events occurred near or within fragile sites and other repetitive regions, such as TERT, FN1, MLL4, ROCK1, CCNE1, SENP5, Alu sequences, and microsatellites, which are prone to tumor development and progression." (PMID 28382278, 2017). "Using a commercial array followed by confirmatory qRT-PCR analysis, we found an overall increase in CCNE1, CTGF, and Cyr61 expression in tumor samples compared to control when grouping all HCC samples." (PMID 27605415, 2016). "Meanwhile, E2F1 silencing inhibited tumor cell growth and invasiveness, accompanied by markedly decreased binding of E2F1 at CCND1 and CCNE1 gene promoters in ARID2-depleted cells." (PMID 27351279, 2016). "In fact, miR-16 has been reported to act as a tumor-suppressive miRNA in many cancer types, and multiple apoptosis-related genes are targeted by miR-16, including BCL-2, CCND1, CCND3, and CCNE1." (PMID 26031775, 2015). "Analytical sensitivity for detection of somatic amplifications of CCNE1 and ERBB2 genes in tumour samples—concordance between ISH assay and results from the MLPA-seq." (PMID 26569395, 2015). "We show that this method can detect BRCA1, BRCA2, ERBB2 and CCNE1 copy number changes in DNA extracted from snap-frozen and FFPE tumour tissue, with 100% sensitivity and >99.5% specificity." (PMID 26569395, 2015). "CCNE1 and SMAD3 were strongly stained in the tumor tissues but were weak in the normal tissues, whereas the ALDH2 staining showed the reverse pattern." (PMID 25408144, 2014). "The protein levels of Cyclin E1, Cyclin D3, Cyclin D1,Cyclin A2, CDK2 and CDK4 were significantly decreased in tumor tissues harvested from miR-188 injected mice." (PMID 25304455, 2014). "Cyclin E1 and MMP9 expression levels were reduced, indicating that these two downstream genes are regulated by NR5A2 and are suggested to participate in neoplasm proliferation and invasive process induced by miR-139-5p, respectively." (PMID 24204738, 2013). "Immunohistochemical analysis of tumor tissue for molecular targets of cell cycle such as CCND1, CCNE1, pRB and PCNA demonstrated a significant decrease in expression level accompanied by a moderate decrease in KI67 in response to P276-00 treatment." (PMID 23414419, 2013). "As in the initial tumor series, BRCA2, DNMT3B and CCNE1 mRNA levels were significantly higher in patients who relapsed than in those who did not relapse." (PMID 15606925, 2004). "This complex enhances mRNA translation efficiency and upregulates the expression of cell cycle-related genes, such as Cyclin D3 (CCND3) and Cyclin E1 (CCNE1), as well as genes involved in the RPTOR/ULK1/autophagy axis and the PI3K/AKT/mTOR pathway, thereby directly driving tumor cell proliferation." (PMID 41446042, 2025). "In conclusion, patient-derived organoids were successfully established from PARPi-resistant HGSOC cell lines, retaining the original tumor architecture and biomarker expression (EpCAM, CA125, PAX8, HER2, MEK1/2, Cyclin E1), thus validating their use as preclinical models." (PMID 41009433, 2025). "Interestingly, G1/S-specific cyclin-E1, and prolyl endopeptidase FAP were unique in ARMS, denoting its crucial role in cell cycle progression and tumor invasion." (PMID 40710368, 2025). "Furthermore, CCNE1 and CCNE2 generally influence tumor development and progression through the regulation of RB phosphorylation." (PMID 40346052, 2025). "We also performed differential expression analysis without controlling for tumor type, finding CCNE1 to be the single most significant gene in this analysis and with 57% (17/30) of the top 30 genes being found on chromosome 19." (PMID 40112818, 2025).
tumor (continued). "Histopathological and immunohistochemical analyses confirmed that these organoids recapitulated the architectural and molecular features of the original tumors, including expression of established tumor markers (EpCAM, CA125, PAX8) and potential therapeutic targets (HER2, MEK1/2, Cyclin E1)." (PMID 41009433, 2025). "Furthermore, the impacts of circACTN4 on the MYC expression, CCNE1, and CDK4 were detected via immunohistochemistry (IHC) in transplanted tumor tissues." (PMID 40612865, 2025). "In addition, given the high structural and functional similarity between CCNE1 and CCNE2, both genes are essential for tumor cell proliferation." (PMID 40346052, 2025). "We FACS-sorted glyCAF (CD90+CD73+) and non-glyCAF (CD90+CD73−) from Ccne1+ tumor bearing mice and briefly expanded them in vitro." (PMID 38509063, 2024). "By examining spatial distribution of the T cells in these two models, we observed that both CD8+ and CD4+ T cells are significantly more abundant in the inner parenchyma of Vgll3+ tumors than in Ccne1+ tumors, in which CD8+ T cells are instead especially restricted to the tumor margin." (PMID 38509063, 2024). "To further assess whether the reduction of tumor growth upon DOX+GLUT1i is, at least partially, CD8+ T cell-dependent, we performed an analogous experiment in which we depleted CD8+ T cells from Ccne1+ tumor bearing mice before DOX+GLUT1i treatment." (PMID 38509063, 2024). "Accordingly, we hypothesized that different CAF content in Ccne1+ and Vgll3+ tumors is responsible for their distinct immune TME, and especially for blocking T cells at the tumor border in the Ccne1+ tumors." (PMID 38509063, 2024). "CCNE1, the regulator of CDK, is amplified in malignant growths in 7.5% of tumor types." (PMID 38344410, 2024). "Furthermore, it was showed that the inhibitor specific for AURKB (AZD1152) can suppress CCNE1 expression in CRC cells and inhibit tumor cell growth." (PMID 38713155, 2024). "In multivariate analysis, pSTAT1 expression was associated with γH2AX (β = 0.221, P < 0.001), pRPA (β = 0.151, P = 0.006) and c-Myc (β = 0.139, P = 0.023), but not Cyclin E1, when corrected for tumor subtype, stage and grade." (PMID 38167507, 2024). "Previously, it was reported that miR17-5p could repress RBL2, also named P130, to release activating transcription factor E2F4 or CTNNB1, which promoted tumor progression by inducing activation of multiple targeted genes like CCND1 and CCNE1 etc.." (PMID 37506248, 2023). "In addition, NOP14 induced expression of transcription factor E2F4 independent of miR17-5p/P130 signaling, which simultaneously activated a set of targeted genes, such as CCNE1, PIM1, AKT1 etc., to promote tumor proliferation." (PMID 37506248, 2023). "In particular, CCNE1 amplification was found in CSF samples but not in the corresponding primary tumor samples." (PMID 37131253, 2023). "Moreover, integration into the TERT, CCNA2, CCNE1, and KMT2B genes is more common in the HCC group than in the non-tumor group infected with HBV." (PMID 36992198, 2023). "According to the results of genomic differences between primary tumor and post-LM CSF, we speculated that MYC and CCNE1 amplification may be closely related to LM." (PMID 37131253, 2023). "Immune analysis revealed that CCNE1 had a strong correlation with TMB, MSI, neoantigen, and ICP in a variety of tumor types, and this correlation may have an impact on the sensitivity of various cancers to immunotherapy." (PMID 36964635, 2023). "Our study supports the clinical development of therapeutic strategies co-targeting ER, CDK4/6 and CDK2 following progression on AI-monotherapy or combined CDK4/6i and ET to improve survival of patients exhibiting high tumor levels of CDK6, p-CDK2, and/or cyclin E1." (PMID 36153348, 2022).